SNORA71E (small nucleolar RNA, H/ACA box 71E)
Synonyms: ACA39; SNORA39
Gene: Small nucleolar RNA gene on chromosome 20 (38,448,084 to 38,448,215, forward strand). Ensembl gene ENSG00000274309.
Gene Ontology:
Biological process: RNA processing
Cellular component: nucleolus
Homologues: Orthologues: chimpanzee SNORA71 (99% identical), macaque SNORA71 (93% identical), rat Snora71e (80% identical), guinea pig SNORA71E (78% identical), mouse Gm25187 (77% identical), rabbit SNORA71E (76% identical). Paralogues in human: SNORA71C (79% identical), SNORA71D (76% identical), SNORA71A (75% identical), SNORA60 (71% identical), SNORA71 (68% identical), SNORA71 (64% identical), SNORA71 (62% identical).